TSHR (thyroid stimulating hormone receptor)
Diseases named in the same sentence as TSHR in open-access papers (continued):
Sharing a sentence is not in itself a finding about the gene and the disease.
thyroid (92 papers, 2005 to 2025). "In our study, we identified significant genome-wide associations exclusively between common TSHR variants and thyroid-related phenotypes, particularly those within 100 kb of the TSHR gene." (PMID 38194289, 2024). "According to previous reports, the cause of CH in approximately 80%–85% of patients is thyroid dysgenesis (including agenesis, ectopy, and hypoplasia), which is related to gene mutations in TSHR, PAX8, TTF1/NKX2-1, and TTF2/FOXE1." (PMID 37252044, 2023). "It is commonly assumed that thyroid autoantibodies cause TED by eliciting a cross-reactive reaction against the thyrotropin receptor (TSHR) and the IGF-1R on ocular fibroblasts." (PMID 37884559, 2023). "The only other commercially available thyroid nodule molecular diagnostic test in the United States that reports TSHR variants is the Thyroseq Thyroid Genomic Classifier (Thyroseq)." (PMID 36619548, 2022). "In rare situations, thyroid disease is associated with a genetic variation in the thyroid-stimulating hormone receptor (TSHR) or G-protein alpha stimulatory subunit (GNAS) gene such as in McCune-Albright syndrome." (PMID 35413827, 2022). "This phenomenon can be explained by triggered autoimmunity reflected by elevated TSHR-Abs which is caused by the release of autoantigens in the course of thyroiditis and thyroid damage induced by 131I." (PMID 31929534, 2020). "The relationships have been established between genetic variations in TSHR gene and thyroid diseases, such as autoantibody-mediated and genetic variant-induced hyperactivation or repression of TSHR, causing hyper- or hypo-thyroidism." (PMID 32698392, 2020). "Returning to intermolecular epitope spreading, transgenic HLA-DR3 mice immunized with hTSHR DNA develop TSHR antibodies and, in a few mice, mild thyroiditis in association with antibodies to Tg." (PMID 29326719, 2017). "In addition to the primary role of TSHR in thyroid disorders, variations in normal thyroid function are associated with differences in body composition, glucose metabolism, and bone mineral density." (PMID 38194289, 2024). "For example, miRNA-155 and miRNA-146a have been implicated in thyroid carcinogenesis and may influence TSHR expression." (PMID 39125979, 2024). "On the contrary, TSHR is associated with other thyroid diseases." (PMID 23781307, 2012). "Importantly, in Lo-expressors, thyroiditis was associated with the development of antibodies to the mouse TSHR downstream of the A-subunit." (PMID 22970131, 2012). "One might speculate that thyroid-reactive T cells could cause activation of thyrotropin receptor (TSHR)-reactive B cells, secreting TSHR-stimulating antibodies causing hyperthyroidism." (PMID 22216337, 2011). "Our results showed that 6-month in vivo DEHP exposure influenced thyroid hormone levels, and further causes imbalance of the HPT axis of the body through TSH/TSHR signaling, which could be considered as an important mechanism of thyroid toxicity caused by DEHP." (PMID 28054989, 2017). "Data collected included age; gender; thyroid diagnosis and pre- and post-treatment thyroid status; length of GH; TSHR-Ab titres; smoking status; RAI dose and number of treatments; ophthalmology assessment and use of steroid prophylaxis." (PMID 40804643, 2025). "Thyroglobulin (Tg), thyroperoxidase (TPO), and thyroid-stimulating hormone receptor (TSHR) are considered the main thyroid-specific autoantigens involved in the thyroid autoimmune response." (PMID 39124785, 2024). "Understanding the mechanisms and functions of the TSHR is vital for diagnosing and treating thyroid-related conditions." (PMID 38174330, 2023). "The molecular function and clinical role of TSHR have been extensively explored in both benign and malignant thyroid tissues." (PMID 32698392, 2020). "The genes associated with thyroid morphogenesis such as NKX2-1, NKX2-5, PAX8, FOXE1, and thyroid-stimulating hormone receptor (TSHR) have been reported to be involved in thyroid dysgenesis." (PMID 32394050, 2020).
thyroid (continued). "While thyroid pathology was difficult to correlate with TSHR antibody responses we made a serious effort to observe changes in retroorbital adipogenesis around the optic nerve of the immunized mice compared to controls as reported by others." (PMID 30666231, 2018). "Based on the high rate of TSHr methylation in papillary thyroid carcinoma, some authors investigated the effect of de-methylating agents in the treatment of thyroid malignancies." (PMID 26519197, 2015). "Interaction between thyroid and breast cancer can occur in the mechanism involving TSHR, common in the adipose breast tissue." (PMID 23680448, 2013). "After treatment with anti-thyroid drugs, both thymic size and density were significantly reduced with a concomitant decrease in thyroid-stimulating hormone receptor antibodies." (PMID 22321290, 2012). "Emerging evidence suggests a potential molecular link between AT and thyroid malignancies, characterized by the co-expression of multiple genes such as TSHR, BTB domain and CNC homolog 2 (BACH2), and forkhead box E1 (FOXE1), along with shared somatic mutations." (PMID 41153734, 2025). "It was demonstrated that TSHR is highly expressed in the OLP lesions of patients with thyroid disease compared with healthy oral mucosa, suggesting that TSHR may be involved in the pathogenesis of OLP." (PMID 41254953, 2025). "The major thyroid autoantigens are thyroglobulin, thyroid stimulating hormone receptor and TPO." (PMID 38013274, 2023). "Given the 96% negative predictive value of an Afirma GSC-B result and the known overall low risk TSHR mutated ITN, it is very unlikely there are many false negative TSHR mutated thyroid nodules." (PMID 36619548, 2022). "Thyroid dysgenesis is caused by genes (thyroid transcription factor-1 [TTF-1], thyroid transcription factor-2 [TTF-2], and paired box 8 [PAX-8]) associated with syndromic CH and those causing non-syndromic CH (thyroid-stimulating hormone receptor [TSHR])." (PMID 34638176, 2021). "In this regard we have recently observed that treating mice with a monoclonal neutral TSHR–Ab induced thyroid pathology supporting our hypothesis that such antibodies influence the disease phenotype." (PMID 30666231, 2018). "Deregulation of TSHR seems to play an important role in thyroid carcinogenesis." (PMID 28117295, 2017). "Mouse models have shown that TSHR is required for thyroid carcinogenesis." (PMID 28117295, 2017). "In these patients, TG levels also correlated to serum titers of TSHR antibodies, indicating that not only TSHR but also TG may be released from the thyroid gland in the course of a thyroiditis and home to the orbit where they become targets of autoantibodies and cytotoxic T lymphocytes." (PMID 27014188, 2016). "In addition, screening of the FinnGen database revealed rare functional variants as well as distinct common noncoding TSHR SNPs significantly associated with thyroid phenotypes, but there was no other significant association between TSHR variants and more than 2,000 nonthyroid disease endpoints." (PMID 38194289, 2024). "Generally, various genetic and molecular studies addressed the issue of congenital hypothyroidism (for example, anomalies of TSHR, SLC26A7, JAG1, DUOX2, and FOXE1 gene) linking the thyroid dyshormonogenesis to thyroid dysgenesis." (PMID 38791947, 2024). "The 11 selected thyroid-specific RNA transcripts (TPO, TG, GFRA2, IYD, PDE8B, WDR86, C16orf89, DGKI, DIO2, TSHR, and PAX8) were amplified from healthy volunteers and thyroid patients." (PMID 34512731, 2021). "Two thyroid-related genes, TTR and TSHR, were observed among the top hits." (PMID 41387570, 2025). "The patient had no history of thyroid disorder, no recent use of contrast or iodine, and TSH receptor antibodies (TSHR Ab, also known as TRAb) were negative." (PMID 38800321, 2024). "Maternal thyroid disease is also unlikely to be a major player since its incidence is likely to have remained stable and blocking TSHR antibodies is rare." (PMID 35588090, 2022).
thyroid (continued). "In fact, there are some studies about histological material of thyroid nodules revealing the role of TSHr methylation in the thyroid carcinogenesis; however, data about the TSHr methylation status in FNAC material is lacking." (PMID 26519197, 2015). "Therefore, we consider first the development of antibodies to the immunogens, namely the TSHR A-subunit and in some cases Tg, before considering development of antibodies to TPO, thyroiditis and serum T4." (PMID 22970131, 2012). "The IgG subclass distribution of TSHR antibodies was determined to investigate differences between transgenic mice that could possibly contribute to the lack of thyroiditis in Hi expressor mice primed with CFA+A-subunit protein." (PMID 22970131, 2012).
autoimmune disease (74 papers, 2011 to 2026). A disorder resulting from loss of function or tissue destruction of an organ or multiple organs, arising from humoral or cellular immune responses of the individual to their own tissue constituents. "Common causes are autoimmune disorders that target autoantigens including Tg, TSHR, and TPO, resulting in under- or overproduction of thyroid hormones." (PMID 40429790, 2025). "GD is an organ-specific autoimmune disease in which thyroid-stimulating immunoglobulins (TSI) activate the TSH receptor (TSHR) expressed on thyroid epithelial cells causing an overproduction of thyroid hormones." (PMID 37025408, 2023). "GD is an organ-specific autoimmune disease directly caused by thyrotrophin receptor antibody (TRAb) that binds to the thyrotropin receptor (TSHR), subsequently inducing the synthesis and release of THs, and diffuse enlargement of the thyroid gland." (PMID 37780612, 2023). "These include polymorphisms of TSHR, shown to affect the development of central tolerance and associated with autoimmune diseases, or polymorphisms of PRDM1 found to influence antigen presentation and associated with systemic lupus erythematodes." (PMID 35053465, 2022). "Graves' disease is an autoimmune disease with a prevalence of approximately 2%, which is caused by antibodies developed mainly against thyroid stimulating hormone receptors (TSH-R)." (PMID 34007271, 2021). "GD is an autoimmune disorder, which is caused by activation of the immune system against the endogenous thyroid stimulating hormone receptor (TSHR), with the formation of auto-antibodies that trigger alterations and the clinical symptoms affecting the thyroid, the eye orbit and other tissues." (PMID 37082124, 2023). "It is an autoimmune disease caused by autoantibodies to the TSHR (TRAb)." (PMID 35877662, 2022). "It is an autoimmune disease caused by production of auto-antibodies that activate the thyroid stimulating hormone receptors (TSHR), which is primarily located in thyroid tissues but also expressed in adipose and connective tissues within the retro-orbital area." (PMID 29235518, 2017). "Grave’s disease is an autoimmune disorder whereby TSHR is bound and activated by agonistic autoantibodies circumventing the negative feedback regulation of thyroid hormones and results in hyperthyroidism." (PMID 40429790, 2025). "Graves' disease (GD) is a common autoimmune disorder mediated by thyrotropin receptor (TSHR) autoantibodies." (PMID 40500868, 2025). "Current treatments for autoimmune diseases include inducing immune tolerance through TSHR-specific antigens and several experimental therapies." (PMID 35813642, 2022). "GO is an autoimmune disease in which autoantibodies to the thyroid-stimulating hormone receptor lead to an inflammatory response in the orbital tissues." (PMID 35566475, 2022). "GD is an autoimmune disorder sustained by the abnormal production of autoantibodies to the TSHR, called TSHR autoantibodies (TRAb)." (PMID 36136821, 2022). "What is certain is that it is a self-reactive lymphocyte-induced autoimmune disease in which immune tolerance is lost, leading to an immune response to TSHR that initiates remodeling of the orbital tissue." (PMID 35444685, 2022). "According to the WHO, GD is an autoimmune disorder characterized by the overproduction of thyroid hormones (thyrotoxicosis) due to circulating autoantibodies that stimulate the thyroid-stimulating hormone receptor or thyrotropin receptor (TSHR)." (PMID 41415293, 2025). "In addition, TSHR elevation was only detected in severe COVID-19, which could suggest higher chance for appearance of autoimmune disorders post severe COVID-19 infection." (PMID 34276672, 2021). "As an autoimmune disease, TAO is characterized by sensitive T cells and antibodies against autoantigens, such as thyrotropin receptor (TSHR) and insulin-like growth factor-1 receptor (IGF-1R)." (PMID 37176063, 2023).
thyrotoxicosis (73 papers, 2005 to 2026). A hypermetabolic syndrome caused by the elevation of thyroid hormone levels in the serum. "Sporadic non-autoimmune congenital hyperthyroidism (SNAH) is a rare and persistent form of neonatal thyrotoxicosis caused by activating mutations in the thyroid-stimulating hormone receptor (TSHR) gene." (PMID 41018437, 2025). "Disease diagnosis is confirmed by thyrotoxicosis (excess thyroid hormones), thyroid-stimulating hormone receptor (TSHR)-Ab positivity, goiter, and any associated pathology of eyes (orbitopathy)." (PMID 40427536, 2025). "The thyroid-stimulating hormone receptor antibody (TRAb) transferred from the mother to the fetus stimulates the fetal thyroid and causes fetal thyrotoxicosis." (PMID 38201411, 2024). "Of particular interest, we observed the strongest associations in the FinnGen population between 2 unrelated variants situated in the first intron of TSHR, with 1 variant strongly associated with thyrotoxicosis and the other with autoimmune hypothyroidism." (PMID 38194289, 2024). "Iodine is most likely to precipitate thyrotoxicosis in an iodine deficient population simply by allowing the TSHR-Ab to be effective in stimulating the production of thyroid hormone." (PMID 23878745, 2013). "Sporadic non-autoimmune congenital hyperthyroidism (SNAH) is a rare form of persistent thyrotoxicosis caused by germline activating mutations in the thyroid-stimulating hormone (TSH) receptor (TSHR) gene, distinct from the more common autoimmune neonatal hyperthyroidism." (PMID 41018437, 2025). "Blood tests showed thyrotoxicosis and positive thyroid-stimulating hormone receptor antibodies, and orbital magnetic resonance imaging (MRI) showed enlarged extraocular muscles." (PMID 39882352, 2025). "Laboratory tests confirmed thyrotoxicosis with positive thyroid-stimulating hormone receptor antibodies (TSHR-Ab), leading to a GD diagnosis." (PMID 40895907, 2025). "In patients with GD binding of antibodies to the thyroid-stimulating hormone receptor (TSH-R) increases intracellular cAMP production, resulting in thyroid hormone (TG) release, thyrotoxicosis, and thyrocyte hyperplasia." (PMID 37711890, 2023). "GD is characterized by infiltration of the thyroid with autoreactive T-cells, and the production of thyrotropin receptor (TSHR) autoantibodies (Ab) that activate the TSHR and lead to the clinical manifestations of thyrotoxicosis and diffuse goiter." (PMID 34149627, 2021). "The disease is characterized by the presence of thyroid-stimulating antibodies (TSAb) that target the thyroid-stimulating hormone receptor (TSHR) and act as agonists, leading to chronic hyperstimulation and thyrotoxicosis." (PMID 33921597, 2021). "Due to the structural similarity of the alpha subunits TSH and hCG, the stimulation of the thyroid-stimulating hormone- receptor (TSH-r) by hCG can lead to thyrotoxicosis and worsen the patient's condition, as well as the course of acute respiratory failure." (PMID 31031704, 2019). "The mechanism of TSHR has been extensively investigated, particularly with the help of the stimulatory autoantibodies in the Graves’ thyrotoxicosis patients." (PMID 22792265, 2012). "Complete hydatidiform mole is frequently associated with markedly elevated human chorionic gonadotropin (β-hCG) concentrations, which may result in biochemical or clinical thyrotoxicosis through thyroid-stimulating hormone receptor activation." (PMID 41694925, 2026). "The pathophysiology of GD is connected with the presence of circulating anti-thyroid-stimulating-hormone receptor antibodies (TSH-R), triggering thyroid cells and leading to thyrotoxicosis." (PMID 39795885, 2024). "Thyroid dysfunction has more likely been linked to thyrotoxicosis caused by the subacute thyroiditis phenomena along with ESS in both trials, with antibodies (anti-Tg, anti-TSHR, and anti-TPO) being negative in the majority of circumstances." (PMID 37212057, 2023).
thyrotoxicosis (continued). "Conversely, TSHR, which encodes a thyroid horomone receptor, was top-ranked based on TSS-to-top-SNP distance but not by the omnibus test for thyrotoxicosis." (PMID 33320851, 2020). "The authors suggested that the metabolic effects of thyroid hormones and thyrotoxicosis might play a role and that autoimmunity, although not directly correlated with Thyroid-Stimulating Hormone Receptor Antibody (TRAb) levels, could be an influencing factor." (PMID 41155780, 2025).